WNT5A (Wnt family member 5A)
Diseases named in the same sentence as WNT5A in open-access papers (continued):
Sharing a sentence is not in itself a finding about the gene and the disease.
tumor (continued). "Together, these observations indicate that the WNT5A-L isoform mediates the tumor suppressive functions of WNT5A in colorectal and hematological cancers." (PMID 24260410, 2013). "The list of differentially expressed genes provides information to guide future mechanistic studies aimed at determining how WNT5A affects tumor progression and metastasis." (PMID 23484019, 2013). "Instead, we propose that two distinct WNT5A isoforms, WNT5A-L and WNT5A-S, possess intrinsically different activities and behave as tumor suppressor and oncogene, respectively." (PMID 24260410, 2013). "We propose that WNT5A acts at least in part to inhibit metastasis by regulating movement of tumor cells through these changes in gene expression and transcript splicing." (PMID 23484019, 2013). "All of these genes were down-regulated in WNT5A expressing cells and have known roles in tumor progression." (PMID 23484019, 2013). "Specifically, Wnt5a has been shown to act as a tumor suppressor for colorectal carcinoma by antagonizing canonical Wnt/β-catenin signaling." (PMID 23947922, 2013). "Specifically, we found that an amino-terminally truncated WNT5A isoform exhibits tumor-promoting activities, while the full-length WNT5A protein exhibits tumor-suppressive activities." (PMID 24260410, 2013). "We found a significant positive correlation between Wnt5a expression and the histological grade and pathological stage of the tumor." (PMID 23947922, 2013). "The correlation between Wnt5a immunoreactivity, histological grade, and pathological stage of the tumor was analyzed." (PMID 23947922, 2013). "Wnt5a is known to be frequently up-regulated in various human cancers and to act as a tumor promoter." (PMID 23349696, 2013). "Our studies using primary pulmonary epithelial tissues as well as cell lines identified Wnt5a and Wnt11 as regulators of cadherin expression, most likely the “cadherin switch” that is a characteristic marker of tumour progression." (PMID 23505429, 2013). "Marked expression of Wnt-5a has previously been reported in human metastatic melanoma and a variety of human primary tumor samples." (PMID 24351810, 2013). "Silencing of β-catenin by small interfering RNA was done to determine its role in the Wnt5a-mediated tumor phenotype." (PMID 24156409, 2013). "The role of WNT‐5A in tumor initiation and progression is complex as differences in cellular constitutions such as receptor repertoire can trigger diverse signaling pathways." (PMID 23727359, 2013). "We found that compared to adjacent normal tissues, Wnt5a-overexpressing tumor tissues had elevated expression of vimentin and reduced expression of E-cadherin, indicating the presence of EMT." (PMID 24156409, 2013). "As Wnt5a is a regulator of fibroblast proliferation and resistance to apoptosis increased tissue mass of tumours with high Wnt5a levels is understandable." (PMID 23505429, 2013). "Wnt5a mRNA expression was significantly elevated in 5 of the 7 tumor samples from smokers versus matched normal tissues (p<0.05)." (PMID 23349696, 2013). "Such tumor aggressiveness conferred by Wnt5a is mediated through activation of β-catenin-dependent canonical Wnt signaling." (PMID 24156409, 2013). "In those tumor cells that did express Fzd3, Fzd3 exhibited a pronounced polarised focal intracellular aggregates, suggesting the existence of Wnt5a gradients." (PMID 22384081, 2012). "Molecular mechanism by which Wnt5a affects clinical outcome in PCa is not yet fully understood, although it is likely that Wnt5a has an effect on invasion of tumor cells in PCa, as has been described in other malignancies." (PMID 23342259, 2012). "The Wnt5a-triggered bundling of its receptor Fzd3 provides evidence of Wnt5a concentration gradients projecting into the tumor." (PMID 22384081, 2012). "We here report that Wnt5a is upregulated in SCC and BCC and localised to the leading edge of tumors, as well as tumor-associated fibroblasts." (PMID 22384081, 2012).
tumor (continued). "The capacity of Wnt5a to enhance expression of CREB target genes or to promote tumor-cell growth also was inhibited by treatment with LY294002 or transduction of the cells with Ad-ACREB." (PMID 22403610, 2012). "Immunostaining of the TMA for Wnt5a revealed a cytoplasmic pattern of immunoreactivity in tumor cells in accordance with our previous results." (PMID 23342259, 2012). "Several positive-acting ligands for this pathway, including Wnt3, Wnt3a, Wnt7b, and Wnt5a, are significantly overexpressed in tumor tissue, and mRNA for Wnt3 is about 5-fold more abundant in transgenic mammary tissue than in non-transgenic mammary tissue." (PMID 21304988, 2011). "There are studies within the scientific community on the possible role of Wnt5a in suppressing or promoting tumor progression." (PMID 22039506, 2011). "Despite these differences, Wnt5a methylation was concordantly observed in approximately 20% of tumours from both population." (PMID 21587258, 2011). "In Ontario, Wnt5a methylation was much more common in MSI tumours than in MSS tumours (odds ratio (OR)=6.3, 95% confidence interval (CI)=3.9–10.4, P<10−12)." (PMID 21587258, 2011). "Taken together these data indicate that the role of Wnt5a signaling in the regulation of tumor cell proliferation is uncertain." (PMID 22039506, 2011). "Further evidence of a potential tumour-suppressive role was shown by a synthetic peptide synthesised to mimic the biological properties of Wnt-5a." (PMID 19603030, 2009). "DNIIR and Wnt5a-/- tumours demonstrated an expanded population of K6- and K14-expressing cells typically seen in Wnt/β-catenin-induced tumours." (PMID 19344510, 2009). "Here, we show that dominant-negative interference of TGF-β signalling in tumours results in reduced Wnt5a expression." (PMID 19344510, 2009). "Through inhibiting the activation of canonical Wnt signalling, the expression of Wnt-5a is likely to confer a tumour-suppressive role in tumours that rely on canonical signalling for survival." (PMID 19603030, 2009). "Although there is firm evidence that Wnt-5a has a tumour-suppressive role, a few studies have pointed to Wnt-5a having an oncogenic role in tumours arising from a variety of different tissues." (PMID 19603030, 2009). "Histological evaluation of the tumours by H&E staining revealed the presence of pleomorphic nuclei with high nuclear to cytoplasmic ratios in MMTV-PyVmT:Wnt5a-/- tumours when compared with control MMTV-PyVmT tumours." (PMID 19344510, 2009). "In summary, the similarities observed in Wnt5a-/- tumours to those tumours derived from components of the Wnt/β-catenin pathway provide the first evidence that Wnt5a acts to inhibit the Wnt/β-catenin pathway in the mammary gland." (PMID 19344510, 2009). "Immunostaining and confocal microscopy on sections from control and Wnt5a-/- tumours revealed elevated levels of intracellular β-catenin in the absence of Wnt5a." (PMID 19344510, 2009). "It is likely that the tumour-suppressive and oncogenic effects of Wnt5a are highly dependent on the cell type and context in which the signalling occurs; however, these discrepancies clearly emphasise the need for further investigation." (PMID 19344510, 2009). "The results suggest that TGF-β and Wnt5a redirect tumour phenotype to form tumours similar to those formed by excess Wnt/β-catenin signalling." (PMID 19344510, 2009). "We propose that Wnt5a acts to mediate some of the tumour-suppressive effects of TGF-β by antagonising the Wnt/β-catenin pathway." (PMID 19344510, 2009). "In light of solid credentials in favour of Wnt5a as a tumour suppressor, other studies present evidence for an oncogenic role for Wnt5a." (PMID 19344510, 2009). "To determine if loss of Wnt5a also affected stabilisation of β-catenin in MMTV-PyVmT tumours, we analysed MMTV-PyVmT and MMTV-PyVmT:Wnt5a-/- tumours for differences in β-catenin levels." (PMID 19344510, 2009).
tumor (continued). "The fact that Wnt-5a has been described as both challenges the simplistic classification of genes as tumour promoters or suppressors." (PMID 19603030, 2009). "In contrast, osteoblasts (OBs) exert dual roles, either promoting or restraining tumor growth through context-dependent signaling pathways, including Wnt5a-mediated dormancy and transforming growth factor-beta (TGF-β)-induced epithelial-mesenchymal transition (EMT)." (PMID 42291433, 2026). "Tumor macrophages demonstrated significant upregulation of genes associated with polarization to the tumorigenic and immunosuppressive M2 phenotype (e.g., APOE, CD163, WNT5A, and THBS1)." (PMID 40848148, 2025). "In tumor, desmoplastic fibroblasts and WNT5A+ inflammatory fibroblasts were notably enriched." (PMID 40032993, 2025). "Additionally, a unique subset of WNT5a+ TAMs has been recognized for its ability to boost tumor invasiveness and support angiogenesis, highlighting the diversity and functional variety of TAMs present within the TME." (PMID 41041337, 2025). "Wnt5a, expressed by inflammatory fibroblasts under hypoxic conditions, reinforces tumor angiogenesis suppression through VEGFR1 (Flt1)-dependent pathways and sustains a hypoxic niche that drives epiregulin production thereby potentiating tumor growth and metastasis." (PMID 41403952, 2025). "Furthermore, in the other literature, it has been indicated that miR-26a-5p negatively regulates tumor proliferation and invasion while promoting cell apoptosis by targeting the expression of the WNT5A gene." (PMID 40076587, 2025). "Furthermore, interferon‐associated basal‐like tumor cells secrete BMP2, which induces the expression and activity of NFE2L3, a transcription factor specific to MMP11+ mCAFs, promoting WNT5A expression." (PMID 40552583, 2025). "Among the nine cell states associated with fibroblasts, five (ADAMDEC1+ fibroblast, BMP4+ fibroblast, intestinal smooth muscle, myofibroblast, PI16+ fibroblast) were identified as NAT-enriched, and three (WNT5A+ fibroblast, pericyte, desmoplastic fibroblast) were identified as tumor-enriched." (PMID 40032993, 2025). "The authors believe that it could be explained by the differentiation-dependent role of Wnt5A in maintaining epithelial architecture and restraining tumor aggressiveness, suggesting a potential role in tumor differentiation." (PMID 40943055, 2025). "Notably, Wnt5A expression is observed in 77.6% of GC cases and correlates with deep tumor invasion, lymph node metastasis, and unfavorable prognosis." (PMID 40943055, 2025). "Interestingly in MUC-1, Wnt5A protein hotspots were often localized at the periphery of the tumor spheroid, which furthermore showed signs of potential budding or localized close to highly open chromatin." (PMID 41310103, 2025). "This work demonstrated extensive reprogramming of interstitial lung fibroblasts as a consequence of aging, including the upregulation of the WNT pathway antagonist sFRP1; this inhibited the WNT5A produced by dormant tumor cells, leading to DTC awakening to promote metastatic outgrowth." (PMID 38963567, 2024). "Moreover, Wnt5a+ macrophages promoted CRC cell proliferation, invasion, and migration, and the knockdown of Wnt5a significantly impaired the pro‐tumour functions of tumour‐associated macrophages." (PMID 38872420, 2024). "Additionally, they also found tumor cells responded to the sudden burst of WNT5A-drived CAFs-specific inflammatory signaling pathways by producing heat shock proteins." (PMID 39558960, 2024). "Wnt5a can suppress tumor growth by inhibiting canonical Wnt signaling, depending on receptor type." (PMID 39665023, 2024). "Specific research indicates that Wnt5a is a tumor suppressor, while others propose the contrary." (PMID 39200196, 2024). "Similarly, WNT5A signaling via the FZD2 receptor has been associated with processes such as cell proliferation, dysregulation of tumor microenvironment, cell migration, and therapy resistance that contributes to tumorigenesis." (PMID 38558536, 2024).
tumor (continued). "For example, some literature reports that Wnt5a inhibits tumor growth 53,54." (PMID 38706907, 2024). "Wnt5a was the most highly expressed Wnt in the tumor fibroblasts." (PMID 38191909, 2024). "The mechanisms by which WNT5A can influence cancer development are highly context-dependent and involve the modulation of different signaling pathways, cellular behaviors, and the tumor microenvironment." (PMID 39176352, 2024). "The expression of Wnt5a showed a negative association with the level of tumor differentiation and the aggressive behavior." (PMID 39200196, 2024). "The study also determined that PTEN and WNT5A, as tumor suppressors, were inhibited by miR-26b, however, expression of miR-26b is a predictor of poor prognosis following carcinogenesis, which might be an indication of miRNA tissue-specificity." (PMID 38632250, 2024). "It has also been reported that Wnt5a has both tumour promoting and suppressing functions in CRC." (PMID 36766788, 2023). "Studies indicated that WNT5A might have tumor suppressive roles, at least in some contexts, whereas WNT5B activates the WNT pathway in BBC." (PMID 37584250, 2023). "KLF4 may be involved in tumor development through the WNT5A signaling pathway, a WNT pathway activated by the receptor tyrosine kinase ROR2." (PMID 36761967, 2023). "Here we show that Lin28b/let-7 pathway is indispensable for modulating the expression of Wnt5a in tumor epithelium, which could be secreted and then up-regulates Lin28b in cancer-associated fibroblasts (CAFs)." (PMID 37898598, 2023). "Our data indicated that Wnt5a can serve as a signal transducer between tumor epithelium and CAFs." (PMID 37898598, 2023). "Studies indicate that Wnt5a may promote anti-tumour immune responses by influencing the composition and function of immune cells within the tumour microenvironment." (PMID 38136392, 2023). "WNT5A is known to regulate the proliferation, invasion, and metastasis of tumor cells." (PMID 37534256, 2023). "WNT5a expression is 88.8% (111/125) in the control group and 48.0% (60/125) in the tumor group." (PMID 37335710, 2023). "Given that Wnt5a can promote tumor cell EMT and metastasis by activating the STAT3 signaling pathway, we next investigated whether TCAF2 in TPCs enhanced CRC cell motility and EMT through the Wnt5a/STAT3 signaling pathway." (PMID 37635201, 2023). "In addition, since our data indicated that Wnt5a-Fzd4 pathway is essential for activation of Lin28b, we also tested the role of Fzd4 in tumor growth." (PMID 37898598, 2023). "Since TCAF2 inhibited ion channel activity and expression of TRPM8, we further investigated whether TCAF2 induced Wnt5a expression and tumor metastasis via TRPM8." (PMID 37635201, 2023). "It has been reported that WNT5A regulates heart and lung development, and tumor progression." (PMID 37396938, 2023). "GBM has also been found to induce WNT5A to mediate tumor cell differentiation into endothelium-like cells via the PAX6/DLX5 transcription program, and subsequently recruit peripheral endothelial cells, which form pseudo-blood vessels, thereby facilitating tumor-invasive growth." (PMID 36880534, 2023). "Knockdown of WNT5A in these TAM reduced tumor formation in xenograft experiment with CRC cells." (PMID 36982422, 2023). "What’s more, Wnt5a secreted by tumor epithelium could also upregulate Lin28b in surrounding CAFs even in response to low glucose concentration." (PMID 37898598, 2023). "Supporting a tumor suppressive function of WNT5A, two studies showed that its overexpression in the CRC cell line HCT116 could reduce Wnt reporter activity, β-catenin protein abundance and tumor growth in mouse xenograft experiments." (PMID 36982422, 2023). "HEF1 regulates tumor cell differentiation through the Wnt5a/β-catenin signaling pathway in GC." (PMID 37341987, 2023). "IHC results validated that the protein expression of FAP, BMP1, WNT5A were upregulated in tumor." (PMID 35999201, 2022).
tumor (continued). "It satisfies our precise strategic consideration of tumor radiation sensitization; through the inhibition of Wnt5a or its downstream target gene Beclin1, we can accurately reverse the radiation resistance effect of tumor cells without too many side effects on normal cells." (PMID 35517407, 2022). "In the tumor microenvironment, WNT5A significantly reduces the number of cytotoxic T cells, decreases the presence of M1 macrophages and increases that of M2 macrophages in tumors, leading to immunosuppression in favor of the tumor." (PMID 35625853, 2022). "WNT5A can interact with the tumor, functioning as both a suppressor and a promoter." (PMID 36452484, 2022). "Wnt5a acts as a tumor suppressor by interfering with the canonical β-catenin signaling." (PMID 36072013, 2022). "WNT5A has been reported to possess anticancer or carcinogenic activities, depending on the tumor type and stage, and regulates various cellular responses, including convergent elongation, cell polarity, inhibition of β-catenin signaling-induced cell movement, and axon rejection." (PMID 35595735, 2022). "Apart from direct interaction between osteoblasts and cancer cells, it has also been observed that factors such as type-I collagen, osteopontin, and Wnt5a produced by osteoblasts or the osteoblastic niche could support tumour cell dormancy." (PMID 36307871, 2022). "Also, we measured total WNT5A mRNA levels by qPCR in the tumor cell fraction (CD4 + /CD7 − /CADM1 +) of an HTLV-1 carrier, a smoldering-type ATL patient, and 3 acute-type ATL patients, which were concentrated by the HAS-Flow method." (PMID 33603066, 2021). "Studies in PCa have revealed an ambivalent role of tumor‐derived WNT5A." (PMID 33639039, 2021). "Interestingly, Wnt5a expression was shown to decrease at both mRNA and protein levels in TNBC in association with poor prognosis and Wnt5a signaling was able to suppress tumor growth and metastasis." (PMID 33585487, 2021). "In the first case, the YAP/Wnt5a signaling axis is likely involved in modulating cell migration, while in the latter, it might be related to tumor growth." (PMID 33643710, 2021). "Interestingly, plasma levels of its target gene, WNT5A, in adrenal vein sampling were found to be useful in differentiating tumor localization and estimating postoperative cure." (PMID 34771744, 2021). "In addition, the role of Wnt5a is emerging in the promotion of proinflammatory and immunosuppressive effects in the tumor microenvironment." (PMID 33754039, 2021). "Our findings suggest that externally derived WNT5A as from stroma tissue assessed here, application of recombinant WNT5A or WNT5A overexpression could all lead to a local deceleration of tumor growth and cell turnover." (PMID 33639039, 2021). "It has been shown that invasion induced by tumor-associated macrophages (TAM) requires the positive regulation of Wnt5a to activate Wnt signaling, independent of β-Catenin in breast cancer cells, increasing their invasive capacity." (PMID 33671415, 2021). "Furthermore, overexpression of WNT5A increased apoptosis and decreased proliferation of PCa cells in vitro and reduced tumor burden in vivo." (PMID 33639039, 2021). "However, treatment of tumor burden mice injected with FOSL2-overexpressing NFs using BOX5 (Wnt5a antagonist) mitigated FOSL2-stimulated blood vessels and tumor growth." (PMID 33754039, 2021). "It is to acknowledge that some controversial issues regarding the role of tumor-released WNT5A in mediating CAAs have been highlighted, mainly based on the described ability of WNT5A to induce adipogenesis and on the expression of this ligand also in adipocytes." (PMID 33917351, 2021). "Similarly, loss of Wnt5a, the direct target of FOSL2, in CAFs significantly decreased tumor blood vessel formation and tumor growth." (PMID 33754039, 2021). "Our results are consistent with studies, where WNT5A has tumor‐suppressive effects." (PMID 33639039, 2021).